TERF2IP (TERF2 interacting protein)
Diseases named in the same sentence as TERF2IP in open-access papers:
TERF2IP is named in the same sentence as 30 diseases in open-access papers, as found by Europe PMC text mining. Sharing a sentence is not in itself a finding about the gene and the disease. The quoted sentences say what the papers report.
melanoma (26 papers, 2015 to 2025). A malignant, usually aggressive tumor composed of atypical, neoplastic melanocytes. "Multigene panel testing, including genes like CDKN2A, CDK4, BAP1, POT1, ACD, and TERF2IP, enhances the detection of hereditary melanoma risk." (PMID 39941357, 2025). "Seven ACD and three TERF2IP pathogenic/likely pathogenic variants were totally identified supporting the pivotal role of telomere dysregulation in melanoma susceptibility." (PMID 40869905, 2025). "We also identified spitzoid morphology in melanomas from individuals with variants in TMG other than POT1 (TERF2IP, ACD, and TERT)." (PMID 36876055, 2023). "Telomere maintenance genes such as TERT, ACD, POT1 and TERF2IP were associated to melanoma predisposition previously." (PMID 35085295, 2022). "The main germline ACD and TERF2IP mutations are nonsense mutations associated with increased risk of multiple primary melanomas and earlier age of melanoma diagnosis, with a peak in the second decade." (PMID 34442055, 2021). "POT1, ACD, and TERF2IP are members of the Shelterin protein complex, crucial for the safeguard of telomeres, and have been also described to be mutated in familial melanoma patients." (PMID 34123788, 2021). "The overall contribution of recently identified CM predisposition genes (ACD, BAP1, POT1, MITF, and TERF2IP) to melanoma’s missing heritability is estimated to be about 2%." (PMID 32325837, 2020). "Four dermatopathologists reviewed the histology of melanomas from individuals with germline variants in POT1 (n = 30 melanomas, 17 individuals), TERF2IP (n = 4 melanomas, 3 individuals), ACD (n = 4 melanomas, 2 individuals), and TERT (n = 2 melanomas, 2 individuals)." (PMID 36876055, 2023). "Recently, germline variants in genes involved in telomere regulation, including POT1, TERT, ACD, and TERF2IP, have been identified in melanoma-prone families." (PMID 40851494, 2025). "•Spitzoid morphology is common in familial melanoma cases from individuals with POT1, TERF2IP, ACD, and TERT germline variants." (PMID 36876055, 2023). "Spitzoid morphology was observed in 77% (23 of 30), 75% (3 of 4), 50% (2 of 4), and 50% (1 of 2) of melanomas from individuals with germline variants in POT1, TERF2IP, ACD, and TERT, respectively." (PMID 36876055, 2023). "In the case of sporadic melanomas, comprising more than 90% of all melanomas, several susceptibility loci acting as moderate (BAP1, TERT, POT1, ACD, TERF2IP and MITF) or low penetration genes have been identified." (PMID 36765773, 2023). "We first looked at an extended list of high-risk genes predisposing to melanoma (ACD, CDKN2A, CDK4, POT1, TERF2IP, and TERT) or RCC (CDKN2B, FH, FLCN, MET, PBRM1, PTEN, SDHs, TSCs, and VHL) or both (BAP1 and MITF)." (PMID 34067022, 2021). "Germline CDKN2A mutations occur in 40 % of 3-or-more case melanoma families while mutations of CDK4, BAP1, and genes involved in telomere function (ACD, TERF2IP,POT1), have also been implicated in melanomagenesis." (PMID 26433962, 2016). "Mutations have also been found in other members of the shelterin complex (ACD and TERF2IP) in melanoma families." (PMID 26433962, 2016). "Spitzoid morphology was also more prevalent in melanomas from individuals with TERF2IP, ACD, and TERT variants compared to noncarriers (OR = 82.4, 95% CI: 21.3-494.6; P < .001)." (PMID 36876055, 2023). "The purpose of this study was to perform a mutational analysis of the seven candidate melanoma susceptibility genes (ACD, BAP1, MC1R, MITF, POT1, TERF2IP, and TERT) in high-risk melanoma patients (familial melanoma and MPM) from southeastern Brazil, besides the CDKN2A and CDK4 genes." (PMID 37958811, 2023). "Spitzoid morphology involving at least 25% of the tumor was observed by at least 3 dermatopathologists in 77% (23 of 30), 75% (3 of 4), 50% (2 of 4), and 50% (1 of 2) of melanomas from individuals with germline variants in POT1, TERF2IP, ACD, and TERT, respectively." (PMID 36876055, 2023).
melanoma (continued). "Other genes that may soon be included in hereditary melanoma testing include ACD (adrenocortical dysplasia protein), MC1R, RB1 (retinoblastoma susceptibility gene), and TERF2IP (telomeric repeat-binding factor 2-interacting protein 1)." (PMID 34440462, 2021). "Other high-risk melanoma genes have been discovered: cyclin-dependent kinase 4 (CDK4), BRCA-1 associated protein (BAP1), and recently via exome sequencing of dense melanoma families, several new high-risk genes affecting telomere functions have been identified: POT1, ACD, TERF2IP and TERT." (PMID 25803691, 2015). "Increased genetic risk for melanoma can occur in the context of germline pathogenic variants in high-penetrance genes, such as CDKN2A and CDK4, risk variants in low- to moderate-penetrance genes (MC1R and MITF), and possibly due to variants in emerging genes, such as ACD, TERF2IP, and TERT." (PMID 37958811, 2023). "Furthermore, hereditary melanoma has been associated with germline mutations in high-risk melanoma susceptibility genes (CDKN2A, CDK4, TERT, POT1), polymorphisms in intermediate-risk melanoma susceptibility genes (BAP1, ACD, TERF2IP, MC1R and MITF), and germline missense substitutions in MITF." (PMID 32276436, 2020). "Our study findings support the inclusion of TMG (POT1, TERF2IP, ACD, and TERT) on genetic testing panels when a familial melanoma case exhibits spitzoid morphology in at least 25% of the tumor cells." (PMID 36876055, 2023). "Mutation in additional shelterin complex genes (adrenocortical dysplasia protein homolog, ACD; telomeric repeat-binding factor 2-interacting protein 1, TERF2IP) were found in familial melanoma patients." (PMID 31717496, 2019). "Therefore, panel testing for POT1, TERF2IP, ACD, and TERT should be considered when familial melanoma cases exhibit spitzoid differentiation." (PMID 36876055, 2023). "Compared to noncarriers (n = 139 melanomas), POT1 carriers (OR = 225.1, 95% confidence interval: 51.7-980.5; P < .001) and individuals with TERF2IP, ACD, and TERT variants (OR = 82.4, 95% confidence interval: 21.3-494.6; P < .001) had increased odds of spitzoid morphology." (PMID 36876055, 2023).
glioma (9 papers, 2020 to 2024). A benign or malignant brain and spinal cord tumor that arises from glial cells (astrocytes, oligodendrocytes, ependymal cells). "Glioma exosomes contain hypoxia-enriched miR-1246, which targets telomeric repeat-binding factor 2-interacting protein 1 (TERF2IP)." (PMID 35562884, 2022). "Exosome-derived miRNA-1246 in hypoxic glioma has been proven to be related to the induction of M2 macrophage polarization by targeting TERF2IP." (PMID 34044888, 2021). "Conversely, GASC exosomes were enriched in miR-1246, responsible for glioma immune escape by targeting TERF2IP, and in miR-4516, known to exert a tumor promoting function by regulating the Hippo pathway in glioblastoma." (PMID 33287106, 2020). "EV-miR-1246 from hypoxic glioma cells reprograms macrophages into M2 phenotype by targeting TERF2IP, which further enhances the proliferation, migration and invasion of glioma cells in vitro and in vivo probably by secreting IL10, TGF-β." (PMID 32503543, 2020). "miR-1246, enriched in sEVs derived from hypoxic glioma cells, targets the telomeric repeat-binding factor 2-interacting protein 1 (TERF2IP), which subsequently downregulates the NFκB pathway and activates the STAT3 pathway, leading to M2 macrophage polarization." (PMID 32709110, 2020).
glioblastoma (4 papers, 2020 to 2024). The most malignant astrocytic tumor (WHO grade IV). "We identified an increase in expression of TEP1, TERF1, and TERF2IP in glioblastoma and astrocytoma cell lines compared to HDFa and NHA control cell lines." (PMID 36142793, 2022). "miR-1246 has been identified as the most enriched miRNA in glioblastoma-derived exosomes and mediates glioblastoma-induced protumorigenic macrophage formation by targeting TERF2IP and subsequently activating the STAT3 pathway." (PMID 34532286, 2021).
breast carcinoma (2 papers, 2005 to 2024). "We studied CBFA2T3, FANCA, FBXL8, LRRC29, TERF2 and TERF2IP, six potential breast cancer TSG candidate genes located on the long arm of chromosome 16, which is involved in LOH in more than 50% of breast cancer cases." (PMID 16280054, 2005). "In our study, the identified truncating variant in TERF2IP occurred in a patient who also developed primary breast cancer (BUM4), hinting at a possible tumor predisposition syndrome associated with the TERF2IP gene, similar to the one described for the POT1 gene." (PMID 38892746, 2024).
Aicardi-Goutieres syndrome (1 paper, 2022). Aicardi-Goutieres syndrome (AGS) is an inherited, subacute encephalopathy characterized by the association of basal ganglia calcification, leukodystrophy and cerebrospinal fluid (CSF) lymphocytosis. "They contribute to pathological cell motility, enhancing neointima formation after vascular injury (ACTR2), cerebral vasculopathy in Aicardi–Goutieres syndrome (SAMHD1) and cells’ activation, senescence and apoptosis (TERF2IP)." (PMID 36614026, 2022).
autism (1 paper, 2025). Persistent deficits in social interaction and communication and interaction as well as a markedly restricted repertoire of activity and interest as well as repetitive patterns of behavior. "In VPA females’ model of autism, nooclerin exerted the most pronounced influence on alterations in the transcriptional activities of the tnks genes, telomerase (Tep1, Dkc1) and the shelterin complex (Terf2ip, Pot1a, Tinf2, Tpp1, Trf1 - 2) in the hippocampus." (PMID 40272729, 2025).
chronic lymphocytic leukemia (1 paper, 2025). "In this context, mutations in the following genes of the shelterin protein complex (POT1, TPP1, TERF2IP, and TINF2) have also been associated with familial melanoma, glioma, and chronic lymphocytic leukemia (CLL)." (PMID 40563586, 2025).
COVID-19 (1 paper, 2021). A disease caused by infection with severe acute respiratory syndrome coronavirus 2. "In agreement with our observation that pulmonary MSCs do not activate the NF-kB pathway in severe cases of COVID-19, we observed that only cells from the control group transcribe high levels of the TERF2IP gene." (PMID 35095855, 2021).
glomerulosclerosis (1 paper, 2024). A hardening of the kidney glomerulus caused by scarring of the blood vessels. "In murine disease models and kidney biopsies from glomerulosclerosis patients, injured podocytes displayed reduced activation of TERF2IP within the glomeruli." (PMID 38846934, 2024). "Notably, severe glomerulosclerosis manifests in mice with diminished podocyte expression of TERF2IP, leading to early mortality from renal failure by 8 weeks of age." (PMID 38846934, 2024).
Hypertension (1 paper, 2024). The presence of chronic increased pressure in the systemic arterial system. "In the presence of caffeine, TERF2IP is upregulated, resulting in increased binding and lower expression of KAT8, independently of the genotype, with an expected overall protective effect on hypertension." (PMID 38334359, 2024). "In summary, in the absence of caffeine, TERF2IP binds preferentially to the reference allele at rs4527034, which results in lower expression of KAT8 and reduced risk for hypertension." (PMID 38334359, 2024).
infarction (1 paper, 2015). A localised pathological necrosis of tissue resulting from obstruction of the blood supply usually by a thrombus, an embolus, or vascular torsion. "This study aimed to examine how Rap1, telomeric repeat-binding factor 2-interacting protein 1 (Terf2IP), which is a novel modulator involved in the nuclear factor-kappaB (NF-κB) pathway, regulates the paracrine effects of MSC-mediated heart repair following infarction." (PMID 27551443, 2015).
Obesity (1 paper, 2014). Accumulation of substantial excess body fat. "Additional roles for TERF2IP include prevention of non-homologous end joining and homology-directed repair, protection from obesity via regulation of metabolic genes and regulation of senescence." (PMID 24752326, 2014).
renal cell carcinoma (1 paper, 2023). "Overexpression of TERF2IP has been observed in breast, gastric, non-small cell lung, condylomatous lymphoma, multiple melanoma, colorectal, and renal cell carcinomas." (PMID 37842637, 2023).
tumor (11 papers, 2005 to 2025). "Validation through multiple Immunohistochemistry (mIHC) confirms the prominence of ARL4C, ARPC1B, and TERF2IP in tumor tissue, and their expression were negatively associated with CD8 T cell presence." (PMID 38419085, 2024). "The results showed that the expression of SH2D2A and TERF2IP genes was significantly upregulated in the tumor tissues, whereas the expression of TMSB4X, although also elevated, was not statistically different." (PMID 37842637, 2023). "In our investigation, we substantiated the heightened expression levels of SH2D2A and TERF2IP in tumor tissues based on our analysis of clinical surgical resection samples." (PMID 37842637, 2023). "MiR-1246 targets telomere repeat-binding factor 2-interacting protein (TERF2IP), significantly promoting M2 macrophage polarization by activating STAT3 and inhibiting the NF-κB pathway, leading to enhanced tumor proliferation, migration, and invasion." (PMID 40813760, 2025). "Two genes involved in telomere maintenance, TERF2 and TERF2IP were among those ruled out as tumor suppressors on 16q, as was E2F4." (PMID 16620391, 2006). "Possible candidates CBFA2T3, TERF2 and TERF2IP, FBXL8 and LRRC29 and FANCA were studied for insertion and deletion mutations and for expression differences using quantitative RT-PCR in a panel of tumour cell lines and primary tumours with and without loss of 16q." (PMID 16280054, 2005). "The expression levels of SH2D2A, TERF2IP, and TMSB4X were significantly different between normal and tumor samples of TCGA, while other model genes were not significantly different." (PMID 37842637, 2023).
cancer (9 papers, 2009 to 2024). A tumor composed of atypical neoplastic, often pleomorphic cells that invade other tissues. "It has been shown to play a part in oncogenesis, cancer progression, and the development of resistance to chemotherapy in human cancers, with multiple mutations and diverse expression patterns of TERF2IP reported in cancer contexts." (PMID 38846934, 2024). "Specifically, the potential role of UM as a candidate cancer within the spectrum of cancers linked to pathogenic variants in the TERF2IP gene and other genes associated with the shelterin complex warrants further examination." (PMID 38892746, 2024). "Truncating variants in TERF2IP are exceedingly rare in the gnomAD non-cancer population." (PMID 38892746, 2024). "Notably, TERF2IP expression is increased in d-flow regions of atherosclerotic plaques and has been linked to various cancers, such as breast cancers, gastric carcinoma, non-small cell lung cancer, and mantle cell lymphoma." (PMID 37332576, 2023). "In conclusion, we identified PIK3R1, CCND1, TERF2IP, SLC25A4, CAPN2, and TXN as potential markers associated with both cancer and MN." (PMID 38846934, 2024). "Recently, increasing evidence suggests that telomere maintenance genes, such as TERT, TERC, TERF1, TERF2, TINF2, TERF2IP and POT1 are associated with cancer risk." (PMID 22970196, 2012). "Key pathways, including p90RSK/TERF2IP, TGFβR1/SMAD, and BH4 signaling are explored as potential targets for cancer treatment." (PMID 37332576, 2023). "In the case of G3 cancer, significant reduction in ARRB2 and DLG4 levels and overexpression of TERF2IP and SLC22A2 were observed." (PMID 34768458, 2021). "Our analysis led to the identification of PIK3R1, CCND1, TERF2IP, SLC25A4, CAPN2, and TXN as hub genes, which could potentially serve as targets for interventions in both MN and cancer." (PMID 38846934, 2024). "In metastatic colon cancer, TERF2IP activates NFkB, leading to the phosphatase of regenerating liver 3 (PRL3) activation and increased TERF2IP expression and nuclear export, ultimately promoting cancer cell invasiveness and metastasis." (PMID 37332576, 2023).
TERF2IP also shares sentences with these, for which no sentence is quoted: familial melanoma (4 papers); cutaneous melanoma (3); astrocytoma (1); B-cell lymphoma (1); bacterial infection (1); breast tumour (1); calculus (1); colon cancer (1); colorectal cancer (1); endothelial dysfunction (1); neuromuscular disease (1); oral diseases (1); periodontal diseases (1); renal failure (1); tumor predisposition syndrome (1).